TNF (tumor necrosis factor)
Diseases named in the same sentence as TNF in open-access papers (continued):
Sharing a sentence is not in itself a finding about the gene and the disease.
pulmonary fibrosis (continued). "FZHY and methylprednisolone could attenuate the lung fibrosis and decrease pulmonary TNF-α expression in bleomycin induced fibrotic mice, without difference between two treatments." (PMID 35548340, 2022). "Reduced the levels of caspase-3, IL-1β, TNF-α, TGF-β, HYP, 3-NT, and 4-HNE; increased the levels of Nrf2, HO−1, NQO1, SOD1, and CAT; alleviated BLM-induced alveolar epithelial cell apoptosis, alveolitis, collagen accumulation, lung oxidative stress, and lung fibrosis." (PMID 36139759, 2022). "Down-regulates MDA, TNF-α and IL-6 expression; increases SOD activity; inhibits epithelial–mesenchymal transition; and slows the development of pulmonary fibrosis by inhibiting oxidative stress and inflammation in the lung tissues of mice with pulmonary fibrosis." (PMID 35566359, 2022). "The same study revealed that intraperitoneal administration of hAECs could downregulate proinflammatory cytokines such as TNF-α, TGF-β, IFN-γ, and IL-6 and also diminish subsequent pulmonary fibrosis by lowering pulmonary collagen deposition, levels of α-SMA, and inflammatory cells infiltration." (PMID 35337387, 2022). "At the same time, TNFα may be used a therapeutic agent that can resolve the established pulmonary fibrosis, further confirming that we do not have a clear picture of mechanisms and pathways of fibrosis." (PMID 34708034, 2021). "In lung tissue specimens, TNF-α and IL-1β were overexpressed in acute pulmonary fibrosis while presented a low expression level in old IPF patients, suggesting that TNF-α and IL-1β may be involved in the initiation of pulmonary fibrosis." (PMID 34393772, 2021). "Downregulated expression of TNF-α, IL-1β, IL-6 and IL-10 proteins indicated that AD-MSCs can also protect the lungs from injury and fibrosis through an anti-inflammatory process, which was consistent with ample experimental evidence in MSC-treated pulmonary fibrosis." (PMID 29673394, 2018). "The underlying mechanisms of the good protective effect of CAPE may be attributed to modulation of TGF-β1, TNF-α and PGE2 levels, decrease in collagen content, improvement of pathologic changes, and decrease in the fibrotic grade in BLM-induced pulmonary fibrosis in rat." (PMID 23997916, 2013). "Since TNF-α overexpression alone does not induce pulmonary fibrosis, TNF-α overexpression may sensitize the rats to fibrotic agents." (PMID 21961991, 2011). "We hypothesize that the lack of differences between patients with and without pulmonary fibrosis may be an effect of the influence of other factors like cytokines (tumor necrosis factor, IL-10), immunosuppressive therapy or the predominance of non-active SLE patients in the study." (PMID 24492930, 2014). "Our findings further indicate that TGF-β and oxidative stress, but not TNF-α, contribute to upregulation of GPX3 in lung fibrosis in a cell-type-specific manner." (PMID 27435875, 2016).
sarcopenia (418 papers, 2005 to 2026). Progressive decline in muscle mass due to aging which results in decreased functional capacity of muscles. "Increased CRP and TNF-α levels are associated with sarcopenia in older adults, suggesting a role of systemic inflammation in its pathogenesis." (PMID 42267078, 2026). "The meta‐analysis demonstrated that per 1 pg./mL increase in TNF‐α was significantly associated with a higher risk of sarcopenia overall (crude OR = 1.21; 95% CI: 1.10–1.33; I2 = 44.6%; p < 0.001)." (PMID 41457350, 2026). "Chronic systemic inflammation (e.g., IL-6, TNF-α–driven pathways) promotes proteolysis and metabolic derangements, and sarcopenia has been linked to dysregulated immune cell function and reduced antitumor immunity." (PMID 41597384, 2026). "This study aimed to examine the association of biomarkers recommended by the ESCEO guidelines—including adiponectin, myostatin, P3NP, CRP and TNF‐α—with sarcopenia diagnostic criteria using plasma‐derived EV markers in a prospective cohort." (PMID 40162588, 2025). "This process is marked by the upregulation of inflammatory biomarkers such as C-reactive protein (CRP), IL-6, and TNF-α, all of which are associated with the development of sarcopenia." (PMID 39940321, 2025). "In the pathogenesis of sarcopenia, the upregulation of TNF‐α and activation of the NF‐κB pathway are closely associated with muscle atrophy." (PMID 40255543, 2025). "One of the major underlying mechanisms of sarcopenia is chronic inflammation, often driven by pro-inflammatory cytokines such as IL-6 and TNF-α." (PMID 40843723, 2025). "Classification-CRP is significantly elevated in SO, with WBC serving as a specific marker, while the selective association of TNF-α with sarcopenia suggests the existence of subtype-specific pathways driving chronic inflammation." (PMID 40507924, 2025). "On one hand, anti-TNF therapy has been shown to reverse sarcopenia; on the other hand, sarcopenia has been associated with nonresponse to anti-TNF treatment in patients with IBD." (PMID 40616584, 2025). "Certain inflammatory pathways involve substances like IL-6 and TNF are implicated in both sarcopenia and OSA." (PMID 40055243, 2025). "Pro-inflammatory cytokines such as tumor necrosis factor-α and interleukin-6 can cause chronic low-grade inflammation, which contributes to the development of sarcopenia and the pathogenesis of GAD." (PMID 40373026, 2025). "A recent systematic review and meta-analysis on geriatric diseases also supports this, highlighting elevated TNF-α and IL-1β levels as being associated with sarcopenia and frailty." (PMID 39847510, 2025). "Studies on the pathogenic mechanisms of sarcopenia and low muscle density have shown that interleukin-6 (IL-6) and TNF-α play key roles." (PMID 39963665, 2025). "The role of circulating pro-inflammatory cytokines (interleukin (IL)-6, tumor necrosis factor (TNF), or IL-1b) as a risk factor in cardiovascular and neurodegenerative diseases is well established, as well as its association with sarcopenia and frailties." (PMID 41227378, 2025). "A study of the association between TNF-α and sarcopenia showed that increased levels of TNF-α were related to decreased skeletal muscle mass and strength." (PMID 40265008, 2025). "TNF-α is a major pro-inflammatory cytokine that plays an important role in various chronic disease-associated sarcopenia." (PMID 41140691, 2025). "TNF-α boosts ubiquitin-dependent protein degradation and triggers apoptosis, which has been associated with sarcopenia." (PMID 40098209, 2025). "For example, in sarcopenia, it was found that the reduction in muscle mass was associated with an increase in the secretion of IL-6, TNF-α, and IL-1β by the intramuscular adipose tissue." (PMID 40001498, 2025). "Analysis of inflammatory profiles revealed significantly elevated CRP levels in SO, with WBC as a specific marker, while TNF-α was associated with sarcopenia, suggesting a subtype-specific role of chronic inflammation." (PMID 40507924, 2025).
sarcopenia (continued). "Pulmonary impairment is also often associated with elevated pro-inflammatory cytokines, such as IL-6 and TNF-α, which have been implicated in the pathogenesis of sarcopenia." (PMID 40712241, 2025). "The pro-inflammatory cytokines (such as interleukin-6 and TNF-α) produced during RA development are associated with proteolysis and resting energy expenditure, which are contributors to sarcopenia." (PMID 38638121, 2024). "One of the mechanisms underlying the onset of sarcopenia involves the activation of NF-κB by TNF-α signaling." (PMID 39408262, 2024). "Previous epidemiological studies have consistently shown a strong association between sarcopenia in older adults and elevated levels of proinflammatory cytokines, particularly tumor necrosis factor‐alpha (TNF‐α)." (PMID 39076122, 2024). "The level of circulating pro-inflammatory cytokines (interleukin (IL)-6, tumor necrosis factor (TNF) or IL-1β) is a risk factor in cardiovascular and neurodegenerative diseases and is also associated with sarcopenia and frailties." (PMID 38495887, 2024). "Previous study also confirmed that sarcopenia was associated with systemic inflammation as evidenced by elevated levels of TNF-α and IL-6." (PMID 38411849, 2024). "Thirdly, sarcopenia was linked to protein hydrolysis cascades, such as TNF-α, which was demonstrated to promote tumor migration and was associated with a worsening prognosis in BC." (PMID 39061745, 2024). "With regard to TNF-α, high circulating levels were associated with an 8-fold increased risk of sarcopenia in elderly subjects, while its pharmacological blockade prevented sarcopenia and extended survival in aged mice." (PMID 39334732, 2024). "TNFα is also linked to sarcopenia because this pro-inflammatory cytokine is known to be associated with other factors that contribute to sarcopenia, including protein degradation, reactive oxygen species (ROS) accumulation, and apoptosis." (PMID 38732615, 2024). "MCR was significantly associated with IL-10, IL-10 to TNF-α ratio, sarcopenia, body fat indices and systemic inflammation." (PMID 37371414, 2023). "Elevated levels of inflammatory cytokines, such as IL-6 or TNF-alpha, have been associated with muscle wasting and increased risk of sarcopenia." (PMID 36984525, 2023). "A clinical study demonstrated that reductions in the plasma TNF-α and IL-6 values were positively linked to improvements of diagnostic parameters of sarcopenia in HIV-infected individuals who underwent resistance and aerobic exercise training." (PMID 37589754, 2023). "It has been shown that sarcopenia is associated with a higher level of systemic inflammation and a lower level of anabolic hormones indicated by an increase in Tumor Necrosis Factor-Alpha (TNF-α) and a decrease in IGF-1 in elderly humans (≥60 years)." (PMID 38132107, 2023). "Elevated serum levels of inflammatory markers (such as CRP), and pro-inflammatory cytokines (such as IL-6 and TNFα) have been linked to poor function, reduced mobility status, and sarcopenia." (PMID 35596881, 2023). "MCR was also significantly associated with low IL-10 and IL-10 to TNF-α ratio after adjusting for sarcopenia and body fat percentage." (PMID 37371414, 2023). "In a Chinese cohort study, high levels of TNF-α (>11.15 pg/mL) were associated with a 7.6-fold increased risk of sarcopenia." (PMID 37299588, 2023). "Co-treatment of C2C12 myotubes with IFN-γ and TNF-α is a typical in vitro atrophy model used to study sarcopenia, which is associated with chronic muscular inflammation." (PMID 38004107, 2023). "The upregulation of TNFα is thought to cause muscle proteolysis, which results in muscle loss and sarcopenia." (PMID 35596881, 2023). "We thus used TNF-α as a stimulator of myotubes to further investigate mechanism underlying how TNF-α induces sarcopenia by regulating pyroptosis and the possible crosstalk between apoptosis and pyroptosis." (PMID 36823174, 2023).
sarcopenia (continued). "According to several horizontal and longitudinal studies, sarcopenia is associated with high levels of proinflammatory cytokines, including tumor necrosis factor-α (TNF-α), interleukin-6 (IL-6), and C-reactive protein (CRP)." (PMID 38260146, 2023). "Chronic inflammation related to the aging process, which is defined by elevated levels of interleukin-6 and tumor necrosis factor-α, has been a causal factor of decreased cognitive performance and the presence of sarcopenia in the elderly population." (PMID 36901167, 2023). "An increased serum level of TNF-α has been regarded as an important inflammatory marker associated with sarcopenia." (PMID 36823174, 2023). "Low-grade chronic inflammation, produced by slight elevations in circulating pro-inflammatory mediators (such as C-reactive protein (CRP), tumor necrosis factor (TNF), and IL-6), is among the causes of inducing sarcopenia." (PMID 38069224, 2023). "Protein kinase B signaling and nuclear factor κB via the secretion of transforming growth factor-β, IL-6 and TNF-α was associated with sarcopenia." (PMID 35711555, 2022). "In the current study, we investigated the association between the presence of sarcopenia and inflammatory markers including TNF-a, IL-6, and hs-CRP." (PMID 35361818, 2022). "Physical inactivity, oxidative stress, inflammatory cytokines (such as IL-6 and TNF-α), reduced microvascular flow to muscles, and inadequate energy intake were regarded as common features linked with chronic lung diseases and sarcopenia." (PMID 36388101, 2022). "In sarcopenia, there is an increase in the levels of inflammatory factors, including TNF-α, IL-1, and IL-6, and this increase is associated with a decrease in muscle mass." (PMID 35250869, 2022). "An elevated TNF-α is associated with a higher risk of sarcopenia, while variances perceived in other inflammatory markers, such as CRP, are associated with select muscle indices found only among elderly women with sarcopenia." (PMID 36291982, 2022). "This study confirmed that an increased plasma level of TNF-α was associated with sarcopenia in elderly individuals residing in the agricultural and pastoral areas of Xinjiang, China." (PMID 36160136, 2022). "To investigate this, we measured serum concentrations of the inflammatory cytokines IL-6, TNF-α, and IL-17A and estimated the association between IL-6 and IL-17A levels in elderly individuals with sarcopenia." (PMID 35237317, 2022). "Multiple studies have shown that sarcopenia is associated with a significant increase in pro-inflammatory cytokines, including TNF-α, IL-6, and C-reactive protein." (PMID 36002808, 2022). "Previous study in COPD shown that serum TNF-α levels are significantly associated with grip strength and skeletal muscle mass, which are important determinants of sarcopenia in patients with stable COPD." (PMID 35903456, 2022). "The elevated levels of TNF-α at levels higher than 70 ng/mL also translated to a higher risk of sarcopenia." (PMID 36291982, 2022). "Previous studies indicated that a systemic inflammatory factor (TNF-α) was associated with sarcopenia in patients with COPD, and resistin is involved in the activation of multiple inflammatory signaling pathways." (PMID 35903456, 2022). "The results of the present study suggest that an increased plasma level of TNF-α is significantly associated with sarcopenia among elderly individuals residing in Xinjiang’s agricultural and pastoral areas." (PMID 36160136, 2022). "Reduced insulin signaling and increased levels of inflammatory cytokines such as interleukin (IL)-1, IL-6, and tumor necrosis factor-alpha have been suggested to be associated with sarcopenia." (PMID 36143016, 2022). "Although the mechanisms underlying cytokines and disability remain to be determined, it is plausible that cytokines (e.g., IL-6, IL-1 and tumor necrosis factor-α) directly cause sarcopenia and functional impairments." (PMID 35492728, 2022).
sarcopenia (continued). "Serum TNF‐α and IL‐6 are increased in the elderly and associated with sarcopenia and elevated risk for mortality." (PMID 34708577, 2022). "Fourthly, we included the most common inflammatory markers such as hs-CRP and IL-6, although many others (TNF-α, IL-10, etc.)that have been implicated in sarcopenia." (PMID 34911470, 2021). "Pro-inflammatory cytokines, such as interleukin (IL)-6 and tumor necrosis factor (TNF)-alpha, are associated with sarcopenia." (PMID 34403431, 2021). "Current research shows that greater “body adiposity”, “scenarios of insulin resistance”, and “sarcopenia” are associated with increased systemic levels of various inflammatory markers (particularly IL-6 and TNFα)." (PMID 35010928, 2021). "There is growing evidence that increasing pro-inflammatory markers such as TNF-α, IL-1β, IL-6 are the main cause of skeletal muscle wasting and sarcopenia." (PMID 34041251, 2021). "M1 macrophages are an important source of TNF-α and cause muscle aging by affecting muscle cell fusion with sarcopenia and aging muscle fibers." (PMID 33804803, 2021). "Although there is a clear correlation between increased peripheral IL-6 and TNF-α levels with sarcopenia, the causes and mechanisms remain partially unclear." (PMID 34093446, 2021). "Either inflammatory cytokines, including TNF and IL-1β, or anti-inflammatory cytokines such as IL-10 have been implicated in sarcopenia-related frailty in humans and rodents." (PMID 33918334, 2021). "As blood biomarkers have been shown to be associated with the development of sarcopenia, this study will measure common blood biomarkers of IL-6, TNF-α, CRP, GH, IGF-1, and MSTN and FST as outcome measures." (PMID 34348792, 2021). "A low muscle mass was associated with male sex, low BMI, and TNF inhibitor use, and sarcopenia was associated with a low BMI." (PMID 34441751, 2021). "Second, chronic low-grade age-related inflammation, characterized by elevated interleukin-6 and tumor necrosis factor-α, for example, has also been reported as an important causal factor for both sarcopenia and lower cognitive performance." (PMID 34161525, 2021). "Interleukin (IL)-10 concentration in the blood is known to inhibit tumor necrosis factor (TNF)-α, and increases in cytokine levels as a result of aging are believed to be closely associated with sarcopenia." (PMID 34200794, 2021). "Male, low BMI, and use of TNF inhibitors were associated with a low muscle mass, while male sex, old age, and low BMI were associated with sarcopenia in patients with long-standing RA." (PMID 34441751, 2021). "Inflammation due to increased generation of cytokines such as TNFα, IL-1β and IL-6 has been implicated in the pathogenesis of sarcopenia." (PMID 33260150, 2020). "The formation and development of sarcopenia in IBD is associated with pro-inflammatory cytokines such as tumor necrosis factor α (TNF-α), interferon-γ, interleukin-Iβ." (PMID 33050109, 2020). "TNF-α-induced skeletal muscle cells are a useful in vitro model because TNF-α levels are increased during aging and associated with sarcopenia." (PMID 32498474, 2020). "Studies have demonstrated high levels of TNFα in correlation with decline in muscle mass/strength, suggesting an association with sarcopenia and malnutrition." (PMID 32297262, 2020). "Development of sarcopenia has been previously associated with overexpression of pro-inflammatory factors, particularly IL-6, TNF-α, and C-reactive protein." (PMID 33375628, 2020). "It is well established that a chronic low-grade inflammatory profile (CLIP) is associated with TNFα levels and age-related Sarcopenia in older populations." (PMID 31130871, 2019). "In older patients, the immunoregulatory system is often unbalanced toward a pro-inflammatory state, and the accumulation of proinflammatory cytokines such as IL-6 and TNFα is associated with the development of sarcopenia." (PMID 31248132, 2019).